IL10 (interleukin 10)
Diseases named in the same sentence as IL10 in open-access papers (continued):
Sharing a sentence is not in itself a finding about the gene and the disease.
infection (continued). "We also included combinations of stimuli to mimic bacterial response to infection (smooth lipopolysaccharide/sLPS, Pam3CSK4/P3C, CD40 ligand + IFNγ + sLPS/CIL, interleukin-10 + sLPS/LIL10)." (PMID 40866338, 2025). "There were also differences in the slopes of the simple linear regression lines between other proteins (IL-18, C3, IL-10, and CD163) and time post infection that further highlighted the dissimilarity between Cov and nLongC immune recovery (Figure A1)." (PMID 41369364, 2025). "Of note, we reported previously increased levels of IL-10 in response to Salmonella Typhimurium and ETEC infections in animals treated with the CRL1505 or CRL1506 strains." (PMID 40141330, 2025). "The protective advantage of hybrid immunity likely arises from a combination of higher numbers of SARS-CoV-2-specific MBCs, elevated neutralizing antibody titers, and an infection-induced cytokine profile of IFN-γ and IL-10 in CD4+ T cells." (PMID 40170841, 2025). "By day 10 post-infection, infected mice exhibited significantly elevated levels of MCP-1, IFN-γ, IL-12 p70, TNF-α, IL-6, and IL-10 in the brain, indicating a strong inflammatory response." (PMID 40078875, 2025). "Complementary ELISA data demonstrated a significant augmentation in the secretion of cytokines IFN-γ, IL-4, IL-6, IL-17A, TGF-β, GATA-3, T-bet, IL-10, and TNF-α in the Pm_OMVs-infected group relative to the Pm group at 24 hours post-infection (P < 0.01)." (PMID 41306977, 2025). "For both bacteria, the induction of IL-12 peaked at a multiplicity of infection (MOI) of 2–5, while IL-10, known to inhibit the induction of IL-12 cytokines, was induced more slowly and continued to increase at a higher MOI." (PMID 40723887, 2025). "In the rCsCP2 immunized group, IL-2 and IL-4 levels rose from the second and fourth weeks post-infection, while IFN-γ levels decreased noticeably, and IL-10 expression remained unchanged compared to controls." (PMID 40248698, 2025). "The expression of TNF-α, IL-1β, IL-6, IL-10, TGF-β, and hepcidin mRNA in WT increased sharply and reached a peak on day 1 post-infection with A. hydrophila, followed by a decrease." (PMID 40298788, 2025). "In contrast to the IFN-γ response, IL-10 levels were comparable in WT and ISG15−/− mice at early infection time points (3 dpi)." (PMID 40627782, 2025). "Numerical correlations observed for pre-infection cytokines measured in plasma (IL-1β, TNF-α, IL-6, IL-10, IFN-γ and TGF-β) and viral loads in brain, lungs and heart for animals from all the groups of the experiment." (PMID 40969767, 2025). "In the case of Mycobacterium leprae, the pathogen responsible for lepromatous leprosy, its association with HLA-DRB1*15:01 promotes a Th2-type immune response characterized by excessive IL-10 and TGF-β production at foci of infection." (PMID 41425584, 2025). "Tubastatin A, an HDAC6 inhibitor, has been shown to enhance the immune response to M. tuberculosis by decreasing IL-10 levels and increasing TNF-α levels, and increasing the influx of immune cells to the site of infection." (PMID 40141021, 2025). "Offspring of HFD-fed dams exhibited significantly blunted cytokine and chemokine responses during infection, including reduced levels of serum GM-CSF, TNF-α, IL-1β, IL-6, IL-10, and MCP-1 and peritoneal G-CSF, IL-6, and MCP-1." (PMID 40766470, 2025). "After infection, the percentage of CD45+IL-10+ cells in the splenocytes of WT mice was higher than that of IL-20RA-/- mice." (PMID 41550952, 2025). "Consistent with prior reports we observed that bone marrow-derived macrophages (BMDMs) infected with L. interrogans serovar Copenhageni strain Fiocruz L1-130 at a multiplicity of infection (MOI) of 100 elicited the secretion of TNF, IL-10, and IL-6." (PMID 40501870, 2025).
infection (continued). "Additionally, the infection induced upregulation of the pro-inflammatory cytokines such as interleukin-1beta (IL-1β) and interleukin-6 (IL-6), and downregulation of the anti-inflammatory cytokines such as interleukin-10 (IL-10) and transforming growth factor beta (TGF-β)." (PMID 40571943, 2025). "infection that the hybrid Th1/Tfh population producing IFN-γ, IL-21, and IL-10 are likely to concurrently provide cellular protection and limit the large humoral response that leads to hypergammaglobulinemia." (PMID 40356908, 2025). "The vaccine also elicited cytokine and interleukin release, particularly IFN-γ, TGF-β, IL-23, IL-10, and IFN-β, which are crucial for mounting an effective immune response against infection." (PMID 40297578, 2025). "With regards to expression differences of anti-inflammatory (IL-10) and pro-inflammatory (IFN-γ and TNF-α) cytokines between 24 and 48 hr post-infection, significant differences were observed in the results in response to some sensitive and resistant strains." (PMID 38800030, 2024). "Natural regulatory (Foxp3+CD25+CD4+) T cells regulate the production of proinflammatory cytokines during infection, with Foxp3+CD25+CD4+ Tregs promoting IL-10 production." (PMID 39582867, 2024). "After pharmacological treatment it is possible to observe a drop in both IL-10 and INF-γ expression, concomitant to the containment of the infection." (PMID 39359727, 2024). "Collectively, these findings indicate that EIIB in L. monocytogenes LIPI-4 stimulates the release of inflammatory factors IL-1β, IL-6, IL-10, and TNF-α to combat infection." (PMID 39057985, 2024). "Here, we observed that the ratios of Th2 to Th1 cytokines, specifically anti-inflammatory cytokines (IL-4, IL-6, and IL-10) relative to IFN-γ, remained stable throughout the infection." (PMID 39061002, 2024). "We also observed a persistent activation of IL-10 and TGF-β expression, mainly in the acute (8 dpi) but also the late-phases (15 dpi) of infection." (PMID 39201595, 2024). "FoxP3 regulatory T cells have been considered to play a key role in modulation of immune responses during infections as well as the expression of regulatory cytokines TGF-β and IL-10." (PMID 38658996, 2024). "In this study, the levels of IL-1β, IL-6, IL-10, and TNF-α in the sera of mice were measured three days after infection with Lm928, ΔEIIB, and CΔEIIB." (PMID 39057985, 2024). "Infection with T. gondii increased the production of all other cytokines (IL-6, IFN-γ, TNF, IL-10, and IL-17A) in all experimental groups." (PMID 39417497, 2024). "The expression of GM-CSF, IL-4, IL-5, IL-10, IL-13, KC, and VEGF in Th2 cells, and IL-2, IL-4, IL-5, IL-10, and IL-17 in NK cells significantly increased after infection (PBS-treated group)." (PMID 39264964, 2024). "In cells incubated with both microorganisms and infected with rotavirus (pre-infection), we observed a significant (p < 0.05) upregulation of the mRNA levels of SOCS3, IFN-γ, STAT1, and IL-10." (PMID 38791551, 2024). "Although the percentage of CD4+CD69+ and CD4+CD25+ T cells increased with repeat SA infections, only CD4+CD25+ T cells showed increased eGFP (IL-10) expressions with reinfections." (PMID 39681568, 2024). "The IL-10 level showed a noticeable rise in both the challenge group and the cohabitation infection group with the strain S1/△Alr HLJ-27, and the cohabitation infection group exhibited higher levels than the challenge group." (PMID 38430229, 2024). "Specifically, TNFα, IL-1β, IL-6, IL-10, and type I interferons (IFN-β) decreased early during infection in all three regimes of mice immunization with rVSV-HTNV-GP." (PMID 38341504, 2024). "The chronic upregulation of both IL10 and IFNG together indicates recognition of the immune system of infection status but demonstrates an inappropriate response of immune activation." (PMID 39766767, 2024).
infection (continued). "Mice that healed from a primary infection also produced significantly (p < 0.01) lower levels of IFN-γ, IL-4, and IL-10 (p < 0.01) compared to control (naïve) mice." (PMID 38543944, 2024). "These macrophages, in turn, upregulate anti-inflammatory cytokines such as interleukin-10 (IL-10) and downregulate the proinflammatory cytokines such as IL-6 and tumor necrosis factor (TNF-α), which helps in the spread of the infection." (PMID 39204243, 2024). "We found that the VertX mice reported expression of IL-10 in peritoneal cavity CD4+ and CD8+ T cells, in particular at day 6 post infection." (PMID 39440975, 2024). "CA decreased the infection rate by increasing levels of TNF-α, ROS, and NO, and simultaneously decreasing IL-10 levels and iron availability." (PMID 39211053, 2024). "Unexpectedly, we also find that IL-10 drives the differentiation of newly recruited airway effector CD4 and CD8 T cells into tissue resident memory T cells (Trm) after resolution of the infection and has a role in maintaining Trm in the nasal mucosa." (PMID 38950078, 2024). "infection, there are characteristic dynamics in serum levels of TNF-α and IL-10 during the development of the disease." (PMID 39770719, 2024). "Compared with infection alone, levamisole and BMS-1 reduced IL-1β, IL-10, IL-18, TNF-α and IFN-γ mRNA expression and increased IL-2 and IL-8 mRNA expression (P < 0.01)." (PMID 39075562, 2024). "Following an intraperitoneal CVB3/28 infection in DBA/2J mice, cytokine levels (MCP-1, IL-10, TNF-α, IFN-β) were quantified in homogenized cardiac tissues at different time points post-infection." (PMID 38696536, 2024). "The anti-inflammatory cytokines IL-10 and IL-12p70 along with IFN-γ were also secreted at high levels in the infected mice, indicative of active T cell infiltration in the brain during infection." (PMID 38177535, 2024). "The authors found that up to 18 days post-infection, there was a significant production of TNF-α and IL-10 levels from dogs’ leucocytes and splenocytes, but this difference disappeared after 30 days." (PMID 39770719, 2024). "Two-way ANOVAs revealed significant interactions between EcoHIV infection and B/F/TAF treatment for IFNγ, IL-7, IL-10, and RANTES." (PMID 38786105, 2024). "From our previously reported finding, we observed the expression change of IL-10, IL-12, and SHP-1 with different time points of infection." (PMID 38299832, 2024). "Provide a limited cross-protection against the HP-PRRSV strain or NADC34-like strain infection; induce relatively slow CMI, increased production of IL-10, and low lung lesions against co-challenge with PRRSV-1 and PRRSV-2." (PMID 39772049, 2024). "Based on the results, the mRNA levels as well as IL-1β, IL-6, IL-8, IL-10, IL-18, TNF-α and IFN-γ were significantly upregulated, and the IL-2 level was decreased in the infection group compared to the control group (p < 0.05)." (PMID 38582846, 2024). "A number of studies indicate that let-7a/b/c/d/e/f/g/i are frequently downregulated by the HBx protein in early-stage infection in the PME and therefore can fail to modulate inflammatory proteins like Il-6 and IL-10." (PMID 38256049, 2024). "In the present study, haemonchosis elevated IL-3, IL-6, IL-10, and TNF-α gene expressions in abomasum tissue mRNA, which was attributed to the activation of the inflammatory cascade triggered by infection." (PMID 38963478, 2024). "As the duration of infection prolonged, the expression levels of MsDC-SIGN, RAF1, and IL10 remained significantly down-regulated even after 12 h of stimulation in contrast to the group that did not undergo RNA interference." (PMID 38732232, 2024). "Interestingly, we observed a notable increase in Il-10 expression in S. anginosus-infected macrophages, however this elevation likely represents a compensatory reaction to the robust inflammatory activation observed under this infection, similar to LPS-treated controls." (PMID 38289109, 2024).
infection (continued). "We used Ms-pVV2 and Ms-PE_PGRS38 for infection of RAW264.7 macrophages to study their effects on TNF-α, IL-1β, IL-6, and IL-10 mRNA expression." (PMID 38785795, 2024). "The transcription levels observed at the late stage of infection were similar for IL4, IL10 and IL12 but there were significantly increases for YM1 from day 15 to day 30 DPI." (PMID 38511816, 2024). "At the 8th week post-infection, in undernutrition 65% + infection group, PD-1, PD-L1, Bax and ICOS were upregulated and CD3+CD4+ and CD3+CD8+ T cell proportions were decreased, while the level of serum IL-10 was increased and IL-12 p70 was decreased." (PMID 38185681, 2024). "Similar to ROSS strain infection, the expression of TNF-α, IL-6, CCL-2, and IL-10 was reduced upon etravirine treatment compared with DMSO treatment under the LR2006 OPY1 strain challenge." (PMID 39339151, 2024). "These are involved in the regulation of immune responses to infection and inflammation and IRF4 and IL-10 interact to regulate immune responses." (PMID 38762479, 2024). "Forty-eight hours after G. parasuis challenge, IL-1β, IL-10, IL-18, TNF-α and IFN-γ mRNA expression was increased, and IL-2 and IL-8 mRNA expression was decreased in the infection group compared to the control group (P < 0.001)." (PMID 39075562, 2024). "In L. braziliensis, EV‐primed macrophages showed increased production of IL‐1β, IL‐6, IL‐10 and TNF‐α upon infection, suggesting a role of EVs in exacerbating inflammatory responses." (PMID 39113589, 2024). "Further, our CBA analyses highlighted a very low renal induction of IL-10 in comparison to the robust induction of IFN-γ and TNF-α in mice after seven days of infection." (PMID 38787228, 2024). "We found that the mRNAs and proteins of IL-10 and TGF-β1 were upregulated in PRRSV-infected PAMs at any time post-infection." (PMID 38962699, 2024). "The expression level of IL-10 and IFN-γ in the PCV4-inoculated group gradually increased throughout the infection period." (PMID 39135875, 2024). "Second, IL-10-induced JMJD2A and CHD1 can encourage genes desired in the regeneration of tissues after infection and prevent neutrophils from LPS-activation or TNF-preactivation." (PMID 38745328, 2024). "After the piglets were challenged with G. parasuis for 48 h, the IL-1β, IL-10, IL-18, TNF-α and IFN-γ mRNA expression levels in the blood of the infection group were significantly greater than those in the blood of the control group (p < 0.01)." (PMID 39075542, 2024). "Monocytes and macrophages are the main mediators of the inflammatory response during HCV infection, where the overproduction of TNF-α, IL-1, IL-10 and TGF-β influences the course of infection." (PMID 39608222, 2024). "Blocking IL-10 during vaccination enhanced the frequency of IFN-γ+, IL-17+, and IL-22+ T cell subsets at the site of infection, which are critical for protection against S. aureus." (PMID 38973612, 2024). "Our data showed that MHV-A59 infection significantly increased the proportions of TNF+, iNOS+, and IL-10+ macrophages, as well as TNF+ neutrophils, in the lungs of Smurf1−/− animals compared to wild-type animals." (PMID 39452742, 2024). "To determine the effect of C. sorokiniana in HT-29 cells, we studied the mRNA levels of IFN-γ, IL-10, SOCS3, STAT1, and STAT2 genes in cells incubated with C. sorokiniana in the rotavirus pre- and post-infection assays." (PMID 38791551, 2024). "Monocytes travel throughout the bloodstream, detecting and responding to infections or other stimuli by producing inflammatory cytokines such as TNF-α, IL-1β, IL-6, IL-8, IL-10, and IL-12." (PMID 39042701, 2024). "A study by Polari and coworkers described that in the context of human infection by L. braziliensis, the patient’s MΦ increased TLR2 and TLR4 and triggered TNF-α and IL-10." (PMID 37190011, 2023).
infection (continued). "There are evidences that IL-10-dependent regulation of TNF, IL-6, and IL-1 reduces the inflammatory response, also reducing the probability of PB induced by infection and inflammation." (PMID 37340384, 2023). "Infection by T. rubrum was shown to stimulate the activation of nuclear factor kappa beta (NF-κB) and the production of IL-1β, IL-6, TNF-alpha and IL-10 by macrophages." (PMID 36838531, 2023). "Murine bmDCs stimulated with an increasing multiplicity of infection (MOI) of L. acidophilus NCFM responded with a dose-dependent production of IL-12, IL-10, and TNF-α." (PMID 36769058, 2023). "We found that after infection with PRRSV, the production of IL-10 was significantly increased in both PAMs and T cells." (PMID 36992483, 2023). "There was a temporal increase of IL-10+ lung macrophages and DC with MTB infection (except for DC at Day 30 after infection)." (PMID 37965256, 2023). "RT-qPCR analysis showed an increase of IL-10 and TGF-β transcription in CDV-infected PCLSs at day 1 post infection." (PMID 37112814, 2023). "In the initial stage of infection, groups C and D had lower levels of the proinflammatory cytokines IL-6, TNF-α, and IFN-γ and higher levels of anti-inflammatory cytokine IL-10 than the other groups." (PMID 37051240, 2023). "This reduction was accompanied by a diminished immune response to infection, as indicated by the lowered levels of TNF-α, IL-6, and IL-10 and altered CD4+/CD8+ T-cell ratio." (PMID 38139181, 2023). "The effect of vaccination on cell-mediated immune responses was determined on day 14 post-infection by lymphocyte proliferation assays and assessing IFN-γ, IL-10, and nitrite levels in antigen- and ConA-stimulated cells." (PMID 37317296, 2023). "Our findings are consistent with previous data showing that C57BL/10 mice infected with L. amazonensis, a closely related species to L. mexicana, express low or lack mRNA levels of IL-4, IL-10, and TGF-β in lymph nodes during the late phase of the infection." (PMID 37691941, 2023). "The IL-10 levels gradually increased after infection with two strains within the first 10 days, and at 17 dpi SD53-1603-infected piglets had significantly higher levels of IL-10 than HuN4-infected piglets." (PMID 37920268, 2023). "The uterine macrophages were subsequently infected with WT GB37 or GB37ΔhylB at a multiplicity of infection (MOI) of 1 or treated with control PBS for 4 h, after which IL-10 concentrations in the supernatant were quantified via Luminex." (PMID 37747229, 2023). "Our results show a critical role of early acute TNFα production within the first hour after the infection before the reported IL6 and IL10 production in both experimental and clinical studies." (PMID 37520526, 2023). "Other serum cytokines measured were either unchanged during infection (CCL2) or below the limit of detection (IL-4, IL-1β and IL-10)." (PMID 37837930, 2023). "GO analysis of upregulated infection genes at three weeks indicated immune-related processes, including regulation of the cytokines IL6, IL1, IL12, IL10, IL8 and TNF, as well as macrophage activation, and responses to wounding." (PMID 37200402, 2023). "Treatment of mice with DSS and infection with parasites resulted in increased levels of IL-6, TNF-α, and IL-10 in serum; IL-1β and IL-6 in the colon; and IL-6 in the small intestine." (PMID 36836678, 2023). "Following NE infection in broiler chickens, the proinflammatory factor TNF-α increased and the anti-inflammatory factors IL-4 and IL-10 decreased, disrupting the dynamic balance and promoting inflammation." (PMID 37508014, 2023). "TNF-α, IL-6, IL-8, IL-10, IL-13, and IL-33 in children with HRSV were significantly increased in severe infections compared to mild infections." (PMID 37239461, 2023). "Studies reported that serum TNFα was the first elevated cytokine due to LI infection, followed by the gradual increase in the secretion of IFN-γ and IL-6, while the serum concentrations of IL-10, IL-4, and TGFβ decreased." (PMID 37372164, 2023).